U8 (U8 small nucleolar RNA )
Gene: Small nucleolar RNA gene on chromosome 10 (4,962,436 to 4,962,568, reverse strand). Ensembl gene ENSG00000238840.
Homologues: Orthologues: rabbit U8 (74% identical), mouse Gm24208 (62% identical), dog U8 (60% identical), mouse Gm25369 (54% identical), guinea pig U8 (53% identical). Paralogues in human: U8 (98% identical), U8 (80% identical), U8 (72% identical), U8 (70% identical), U8 (69% identical), U8 (68% identical), U8 (67% identical), U8 (66% identical), U8 (65% identical), U8 (62% identical), U8 (57% identical), U8 (54% identical), and 1 more.